RNU5E-4P (RNA, U5E small nuclear 4, pseudogene)
Gene: Small nuclear RNA gene on chromosome 1 (11,909,808 to 11,909,927, reverse strand). Ensembl gene ENSG00000201801.
Homologues: Orthologues: chimpanzee U5 (94% identical), mouse Gm24871 (88% identical), guinea pig U5 (87% identical), rabbit U5 (87% identical), rat LOC120096440 (87% identical), dog U5 (85% identical), rabbit U5 (85% identical). Paralogues in human: RNU5E-7P (79% identical), RNU5E-6P (78% identical), RNU5A-3P (78% identical), RNU5B-4P (77% identical), RNU5E-8P (76% identical), RNU5F-7P (76% identical), RNU5A-6P (74% identical), RNU5A-4P (73% identical), RNU5A-7P (73% identical), RNU5E-5P (73% identical), RNU5E-10P (72% identical), RNU5F-3P (72% identical), and 13 more.